INS (insulin)
Diseases named in the same sentence as INS in open-access papers (continued):
Sharing a sentence is not in itself a finding about the gene and the disease.
diabetes (continued). "Current studies showed that the pathophysiology of diabetes is not only associated with changes in insulin secretion, but also with abnormal amylin regulation." (PMID 32121443, 2020). "We believe this compound represents a potential oral and/or injectable insulin replacement therapy for diabetes and diseases associated with insulin resistance." (PMID 31378829, 2020). "The insulin signaling pathway consisted of IRS-1/PI3K-Akt signaling which is a major mechanism underlying the development of diabetes." (PMID 32655424, 2020). "Type 1 diabetes (T1D), accounting for ~10% of patients with diabetes, is caused by autoimmune destruction of β-cells leading to insufficient insulin production." (PMID 33542706, 2020). "Defective insulin secretion underlies diabetes mellitus, a disease affecting almost one in eight of the adult population worldwide." (PMID 32350566, 2020). "Disturbances in insulin sensitivity due to the disruption of various molecular pathways cause insulin resistance, which underpins many metabolic disorders, including diabetes, as well as depression." (PMID 32971941, 2020). "Due to the inability to produce insulin, T1D patients are unable to control their glycemia, and even with replacement therapy, i.e., insulin injection, they can develop diabetes-associated complications in multiple organs." (PMID 32983158, 2020). "To investigate the role of diabetes in the development of atrial fibrillation, we used an insulin-deficient diabetic animal model (type 1 diabetes, T1Dx)." (PMID 32903422, 2020). "Diabetes mellitus (DM) is characterized by different metabolic abnormalities, including hyperglycemia, insulin secretion deficiency, insulin dysfunction, and energy metabolism disturbances." (PMID 33363537, 2020). "Given the accurate diabetes assessments within the Rotterdam Study, we were able to address, for the first time, the association between subclinical variations of insulin and glucose levels with atherosclerotic disease." (PMID 31958313, 2020). "After EC risk factors, including BMI, WHR, diabetes, and hypertension, were stratified, the relationships between type I EC risk and total testosterone, androstenedione, insulin and FAI levels were analyzed in total women." (PMID 32913460, 2020). "Diabetes can lead to oxidative stress-induced β-cell loss, resulting in reduced insulin secretion and increased glucose toxicity." (PMID 31906278, 2020). "Part of the explanation for the increased diabetes mellitus prevalence among overweight individuals is related to the increased insulin resistance and decreased insulin sensitivity associated with elevated BMIs37." (PMID 31172682, 2020). "One of the causes of fertility problems in diabetes, is changes in Muc1 expression during implantation.On the other hand, the use of insulin in these patients can even lead to overexpression of this gene and worsen thecondition." (PMID 33098389, 2020). "It was reported that more than hyperglycemia (which is a peculiar condition of diabetes) and associated effects, the insulin resistance phenomenon by itself plays a crucial role during the preclinical stage of AD." (PMID 32733190, 2020). "A clinical research has demonstrated that early modifications of special trace elements can lead to impaired insulin and glucose metabolisms, while on the other hand, diabetes mellitus is said to be linked to trace element disturbance." (PMID 33299532, 2020). "Prior studies have reported that the long-term exposure to PM10 was associated with a greater homeostatic model assessment of insulin resistance (HOMA-IR) and fasting insulin concentrations; therefore, it brings about an increased risk of diabetes." (PMID 32964052, 2020). "Diabetes mellitus (DM) is a clinical syndrome occurring due to an absolute or relative deficiency of insulin, leading to abnormal carbohydrate metabolism." (PMID 32642346, 2020).
diabetes (continued). "In humans diabetics, pre-existing β-cell dysfunction causing defects in insulin secretion are normally present when corticosteroid administration induces diabetes." (PMID 32500084, 2020). "Increased p-IRS-1S312 and p-IRS-1S616 in blood NDEVs indicated the dysfunctional insulin signaling pathway in PD patients, which supports the association reported in previous epidemiological studies about diabetes and PD." (PMID 33344443, 2020). "Diabetes mellitus (DM) is a worldwide metabolic disorder disease caused by pancreatic β cell dysfunction and insulin dysbiosis, and mainly characterized by hyperglycemia and dyslipidemia." (PMID 31790971, 2020). "On the other hand, longer durations of having diabetes, and the combined use of insulin and oral drugs, was associated with poor glycemic control." (PMID 33391919, 2020). "Deletion of GPR4 is associated with lower blood pressure, lower binding to angiotensin II receptor, and increased insulin sensitivity; these aspects are of particular interest as hypertension and diabetes are risk factors associated with COVID-19 mortality." (PMID 33553219, 2020). "In summary, the metabolic level was closely related to insulin function, and the worse the metabolic level, the higher the risk of diabetes." (PMID 32811450, 2020). "Type 1 diabetes mellitus (T1D) is a common pediatric chronic condition characterized by the loss of natural insulin production and inability to regulate blood glucose levels." (PMID 32808936, 2020). "Breast cancer mortality risk was increased in women who had used insulin for more than 3 years; additionally BC risk was associated with the presence of diabetes." (PMID 32334446, 2020). "The laboratory-based diabetes diagnostic tools which are currently available include fasting blood glucose levels, insulin sensitivity indexes, oral glucose tolerance tests (OGTT) and glycated hemoglobin (HbA1c)." (PMID 32708684, 2020). "In insulin-deficient mice with diabetes, the authors found that the FGF21 suppressed the secretion of pro-inflammatory cytokines, enhanced retinal antioxidant defense system, restored disorganized cone photoreceptor segments, and improved the retinal function." (PMID 33213461, 2020). "The interplay between pancreatic insulin production and peripheral resistance to insulin defines the current pathogenic paradigm of the pre-diabetes and diabetes stages of T2D." (PMID 32128655, 2020). "The updated guideline of the American Diabetes Association5, also suggested considering initiating insulin therapy for newly diagnosed type 2 diabetes patients with HbA1c ≥10%." (PMID 31161658, 2020). "Excessive ROS-induced oxidative stress is one of the main mechanisms of the progression of diabetes causing cellular damage and resulting in various gene expression dysregulations which lead to impaired insulin secretion and insulin signaling." (PMID 32245008, 2020). "Type 2 diabetes mellitus (T2DM) is a metabolic disease that is principally caused by impaired insulin signaling and the discontinuation of insulin production in severe cases." (PMID 32842462, 2020). "The accumulation of lipids, particularly TC and TG, in hyperglycemic patients caused by insufficient insulin can lead to diabetes-related complications." (PMID 32425787, 2020). "The STAM model of NASH18 is characterized by the nearly complete loss of pancreatic insulin production with severe hyperglycemia indicating this model represents diabetes-based NASH patients." (PMID 32385406, 2020). "Insulin gene mutations have been identified to cause monogenic diabetes, and most of which developed permanent neonatal diabetes at young ages before 6 months of age in humans." (PMID 32699230, 2020). "Meanwhile, in pre-clinical studies, metformin also induced the protective UPRER function, and TZDs improved insulin sensitivity by upstream mediated attenuation of inflammation and ER-associated apoptosis, thereby ameliorating cardiac function in diabetes." (PMID 33195472, 2020).
diabetes (continued). "Deficiency in insulin secretion, insulin action or both, results in chronic hyperglycemia, the main characteristic of diabetes mellitus, the main treatment to this condition being the use of anti-diabetic drugs that can control glucose levels in the blood." (PMID 32354114, 2020). "When refed carbohydrates, mice quickly developed diabetes demonstrated by loss of insulin-positive cells and increased caspase 3 expression." (PMID 33187118, 2020). "In this regard, hyperinsulinemia is also a common feature of both obesity and diabetes, and high insulin levels have been linked to cell cycle arrest in mouse keratinocytes." (PMID 31940810, 2020). "Patients with treated diabetes are also at risk for hypoglycaemia, especially those whose treatment includes insulin or an insulin secretagogue." (PMID 32907617, 2020). "Diabetes is a global health problem, indicated by a high blood glucose level caused by insufficient insulin production by the pancreas or decreasing insulin sensitivity." (PMID 32733964, 2020). "Metabolic abnormalities observed in diabetes can be caused by the low level of insulin production and/or insulin resistance of the target tissues." (PMID 32155866, 2020). "Type 2 diabetes mellitus is a metabolic disorder caused by abnormal glucose metabolism due to insulin resistance or disrupted B-cell function culminating in abnormal insulin production." (PMID 33022986, 2020). "Among diabetes medications increased MPV was associated with Insulin (β = 0.1341; P = 1.38 × 10−11) and decreased MPV with both Metformin (β = 0.0763; P = 1.99 × 10−6) as well as the sulphonylureas (β = 0.0559; P = 0.0034)." (PMID 32754618, 2020). "Insulin resistance caused by the decrease in insulin sensitivity disrupts the entry of glucose into muscle, liver, and adipose tissue, which eventually leads to diabetes." (PMID 33568996, 2020). "Among the two most well-known types of diabetes, Type 1 is dependent on insulin and it is caused due to insufficiency or dysfunction of insulin." (PMID 33118125, 2020). "The American Diabetes Association describes Diabetes mellitus as a group of degenerative disorders that are demonstrated by hyperglycemia induced by insulin secretion disorders, insulin action or both." (PMID 32544194, 2020). "Dysregulation of insulin production from pancreatic β-cells is one of the key causes of the development of diabetes." (PMID 32560282, 2020). "In human studies, this vitamin has been shown to have beneficial effects in improving insulin sensitivity and reducing the risk of type 2 diabetes mellitus (DM2)." (PMID 32267358, 2020). "Diabetes is one of the prominent chronic diseases caused by either dysfunctional insulin production or failed deployment of insulin." (PMID 33375269, 2020). "Insulin was found to increase EC risk in all stratified data (P < 0.05) except, in women with diabetes (P = 0.137)." (PMID 32913460, 2020). "Obesity is tightly linked to the development of diabetes because it often results in insulin resistance and reduced insulin-dependent glucose uptake into body organs." (PMID 31973745, 2020). "Diabetes mellitus (DM) is a group of metabolic diseases diagnosed by chronic hyperglycemia which is caused by insufficient insulin production or the destruction of pancreatic beta (β)-cells." (PMID 32235681, 2020). "Diabetes is a common chronic metabolic disease characterized by hyperglycemia due to the deficiency of insulin secretion." (PMID 33287318, 2020). "In a survey of risk factors for severe HTG in which 75% had diabetes, 82% of these were receiving insulin treatment." (PMID 33193106, 2020). "Type 2 diabetes mellitus (T2D) is a progressive metabolic disease caused by impaired responses to insulin in the target tissues, such as the liver, skeletal muscle and adipose tissue, and inadequate insulin production from pancreatic islets." (PMID 33633691, 2020).
diabetes (continued). "The American Diabetes Association defines diabetes mellitus as “a group of metabolic diseases characterized by hyperglycemia resulting from defects in insulin secretion, insulin action, or both." (PMID 32775462, 2020). "As stated in the American Diabetes Association guidelines, basal insulin or a basal plus bolus correction insulin regimen is the favorite treatment for noncritically ill hospitalized patients." (PMID 33335527, 2020). "Type 2 diabetes mellitus, which an outcome of impaired insulin action and its secretion, is concomitantly associated with lipid abnormalities." (PMID 33261004, 2020). "Hyperglycemia can be caused by a deficiency of insulin production by pancreatic (Type 1 diabetes mellitus) or insufficiency of insulin production in the face of insulin resistance (Type 2 diabetes mellitus)." (PMID 32872226, 2020). "It has been shown that ceramide plays a significant role in diabetes by inducing β-cell apoptosis, modulate insulin signaling and causing insulin resistance." (PMID 33033923, 2020). "Impaired cellular response to insulin, known as insulin resistance (IR), is a hallmark of type 2 diabetes and contributes to the systemic downstream detrimental effects of diabetes." (PMID 32192190, 2020). "Unsurprisingly, insulin treatment was associated with hospitalization (OR of 3.83), and hospitalized patients very frequently exhibited complications of diabetes (microvascular and macrovascular complications) compared to outpatients." (PMID 33233575, 2020). "Type 2 diabetes mellitus is primarily caused by insulin resistance (IR) in insulin-sensitive tissues, including liver, white adipose tissues (WAT), and skeletal muscles." (PMID 33061888, 2020). "In particular, the anti-diabetic effect of ginger and the gingerols, shogaols, and paradols is already known to improve insulin sensitivity and decrease the risk of diabetes mellitus." (PMID 31991895, 2020). "The liver as a major target organ of insulin plays key roles in lipid metabolism, and fatty liver is a major risk factor of diabetes." (PMID 31790971, 2020). "Better insulin sensitivity in long-term DIALONG RPs would be in agreement with the recent report from the Swedish National Diabetes Registry showing gradually increased risk of CVD-related death with declined eGDR50." (PMID 32665614, 2020). "Other proposed mechanisms such as chronic low-grade inflammation, insulin dysregulation, and vascular dysfunction have also been implicated in the development of diabetes-associated cognitive dysfunction." (PMID 32407347, 2020). "Diabetes mellitus (DM), a chronic metabolic disease, is caused by the pancreas' inability to produce/secrete insulin or the inability of the body to use insulin effectively." (PMID 32118053, 2020). "Phlebotomy improved insulin sensitivity in humans by reducing body iron levels, which suggests a link between iron overload and diabetes risk." (PMID 32585827, 2020). "Further studies are needed to elucidate the findings of increased all-cause mortality risk in patients receiving basal insulin, especially those with advanced diabetes." (PMID 32238842, 2020). "Diabetes is a metabolic disorder caused by genetic and environmental factors, which lead to insufficient insulin secretion." (PMID 32664229, 2020). "The increased expression of both proteins can be associated with an enhanced insulin sensitivity and the capability to prevent the impaired muscle glucose metabolism that is characteristic of diabetes mellitus and other metabolic syndromes." (PMID 32092940, 2020). "Diabetes mellitus is a metabolic disorder resulting from either loss of insulin producing cells, insufficient insulin action, or both." (PMID 32214398, 2020). "Among patients allocated to intensive blood glucose control, metformin showed a greater effect than chlorpropamide, glibenclamide, or insulin for any diabetes-related endpoint (p = 0.0034), all-cause mortality (p = 0.021), and stroke (p = 0.032)." (PMID 32489427, 2020).
diabetes (continued). "In 2006, this group reported successful treatment of mice with STZ-induced diabetes by intramuscular injection of an adeno-associated vector (AAV) encoding the genes for insulin and glucokinase." (PMID 32880857, 2020). "Diabetes mellitus (DM) is a chronic systemic metabolic disease caused by absolute or relative deficiency in insulin secretion in the body." (PMID 31668144, 2020). "In this epidemiological study, plasma IL-13 was inversely linked with progression from normoglycemia to pre-diabetes, incidence of type 2 diabetes, and initiation of insulin therapy." (PMID 32948777, 2020). "Diabetes represents a group of metabolic diseases characterized by hyperglycemia caused by defects in insulin secretion or impaired biological effects." (PMID 33164904, 2020). "Visceral obesity and the metabolic syndrome are associated with an increased risk of developing CVD, which is exacerbated when overt diabetes develops as a result of insulin secretion failing to adequately compensate for insulin resistance." (PMID 32158768, 2020). "A 45-year-old man with underlying uncontrolled diabetes mellitus who had stopped taking his daily dose of insulin since the last 4 days, presented with pain in the abdominal area of one-day duration." (PMID 32566332, 2020). "As visceral fat is strongly linked to diabetes, cardiovascular risk, and cancer, these findings have implications beyond metabolic diseases and indicate the necessity of strategies to resolve insulin resistance of the human brain." (PMID 32296068, 2020). "Up to 50% of infantile cystinosis patients by the second decade of life develop slow progressive loss of insulin secretion and C-peptide production leading to glucose intolerance and diabetes mellitus." (PMID 33179602, 2020). "In our research, several genes, such as ABCC8 and KCNJ11, related to insulin and diabetes and encoding Kir6.2 and SUR1 have also been found in the ceRNA network." (PMID 32906679, 2020). "Here we report a case with severe hypouricemia accompanied by diabetes with impaired insulin secretion where whole exome sequencing revealed gene mutations responsible for these metabolic disorders." (PMID 32375679, 2020). "Alterations in the gut microbiota community can modulate insulin secretion and sensitivity, thus contributing to diabetes susceptibility." (PMID 33322411, 2020). "Although it is obvious that proper insulin injection is important to good glucose control with lowering the risk of diabetes related complications, recent studies showed that only too few patients can understand this problem." (PMID 32071879, 2020). "In our study, a non-Euro Caucasian origin, previous delivery of a LGA, late institution of treatment, and insulin therapy were associated with failure of diabetes management." (PMID 32346630, 2020). "There are rs12255372 and rs7903146 polymorphisms, when there is insufficient insulin in the body, as its production is disturbed, resulting in a high risk of type 2 diabetes mellitus." (PMID 32230794, 2020). "The critical role of β-cells in driving diabetes risk is further confirmed by genome-wide association studies, which find that most loci influencing T2D risk are involved in regulating insulin secretion." (PMID 33542706, 2020). "Mitochondrial dysfunction has been proposed to cause diabetes through induction of insulin resistance in both muscle and liver via a buildup of excess lipids as well as through a decrease in insulin secretion resulting from lower beta cell ATP content." (PMID 33046063, 2020). "In 2013, this group published the results of treatment of chemically induced diabetes in 4 dogs using the same principle: intramuscular injection of an AAV vector encoding the insulin and glucokinase genes." (PMID 32880857, 2020). "A prospective study showed older men with diabetes on insulin sensitizers such as metformin had less muscle mass loss compared to men with untreated diabetes or with diabetes treated without insulin sensitizers." (PMID 32433712, 2020).